NELFE (negative elongation factor complex member E)
Description:
Essential component of the NELF complex, a complex that negatively regulates the elongation of transcription by RNA polymerase II. The NELF complex, which acts via an association with the DSIF complex and causes transcriptional pausing, is counteracted by the P-TEFb kinase complex. Provides the strongest RNA binding activity of the NELF complex and may initially recruit the NELF complex to RNA. (Microbial infection) The NELF complex is involved in HIV-1 latency possibly involving recruitment of PCF11 to paused RNA polymerase II.
Synonyms: NELF-E; RD; RDBP; D6S45; RDP
Tractability: Small molecule: a structure with a bound ligand is known. Antibody: its Gene Ontology location is reachable by antibodies, with high confidence. PROTAC: UniProt records ubiquitination sites on it; ubiquitination databases record sites on it; its protein half-life has been measured.
Gene: Protein-coding gene on chromosome 6 (31,952,087 to 31,959,038, reverse strand). Ensembl gene ENSG00000204356.
Subcellular location: Nucleus; Chromosome
Subcellular location (Human Protein Atlas): Nuclear bodies; Nucleoplasm
Pathways (Reactome):
Disease: Abortive elongation of HIV-1 transcript in the absence of Tat; Formation of HIV elongation complex in the absence of HIV Tat; Formation of HIV-1 elongation complex containing HIV-1 Tat; Formation of the HIV-1 Early Elongation Complex; HIV elongation arrest and recovery; Pausing and recovery of HIV elongation; Pausing and recovery of Tat-mediated HIV elongation; Tat-mediated HIV elongation arrest and recovery; Tat-mediated elongation of the HIV-1 transcript
Gene expression (Transcription): Formation of RNA Pol II elongation complex; Formation of the Early Elongation Complex; RNA Polymerase II Pre-transcription Events; RNA Polymerase II Transcription Elongation
Gene Ontology:
Molecular function: chromatin binding; mRNA binding; protein binding; RNA binding; RNA polymerase inhibitor activity; nucleic acid binding
Biological process: negative regulation of transcription elongation by RNA polymerase II; transcription pausing by RNA polymerase II; negative regulation of transcription by RNA polymerase II; positive regulation of ERK1 and ERK2 cascade; positive regulation of transcription by RNA polymerase II; regulation of DNA-templated transcription
Cellular component: chromatin; chromosome; NELF complex; nuclear body; nucleoplasm; nucleus
Genetic constraint (gnomAD): Loss-of-function variants: 26 observed, 54.88 expected, observed/expected ratio (o/e) 0.47, 90% interval 0.35 to 0.66. The upper end of that interval is the gene's LOEUF score, 0.66, which puts it in group 2 of 6, group 1 being the genes least tolerant of losing a copy. Missense variants: 403 observed, 523.41 expected, observed/expected ratio (o/e) 0.77, 90% interval 0.71 to 0.84. Synonymous variants: 162 observed, 184.89 expected, observed/expected ratio (o/e) 0.88, 90% interval 0.77 to 1.
Homologues: Orthologues: chimpanzee NELFE (99% identical), rabbit NELFE (96% identical), guinea pig NELFE (95% identical), dog NELFE (91% identical), rat Nelfe (91% identical), mouse Nelfe (90% identical), macaque NELFE (82% identical), pig NELFE (77% identical), tropical clawed frog nelfe (63% identical), zebrafish nelfe (62% identical).
Diseases named in the same sentence as NELFE in open-access papers:
NELFE is named in the same sentence as 16 diseases in open-access papers, as found by Europe PMC text mining. Sharing a sentence is not in itself a finding about the gene and the disease. The quoted sentences say what the papers report.
hepatocellular carcinoma (6 papers, 2019 to 2021). A malignant tumor that arises from hepatocytes. "For instance, RNA-binding protein Nova1 and NELFE promote cancer growth in hepatocellular carcinoma (HCC) cells, whereas RBM47 and RBM43 have been shown to suppress HCC growth." (PMID 34434291, 2021). "For example, NELFE could promote the progression of hepatocellular carcinoma by regulating MYC signaling, and TTP could inhibit cell proliferation and accelerate cell death in lung cancer through the autophagy pathway." (PMID 33193734, 2020). "For instance, oncogenic activation of NELFE promotes hepatocellular carcinoma (HCC) cell proliferation and predicts the strong metastatic potential of HCC cells, whereas knockdown of NELFE results in enhanced cell colony growth of breast cancer cells when treated with estrogen-like reagents." (PMID 33526068, 2021). "Negative Elongation Factor E (NELFE) was also reported to promote hepatocellular carcinoma (HCC) progression by augmenting MYC signaling and selectively controlling MYC-associated genes." (PMID 33923168, 2021).
breast carcinoma (3 papers, 2021 to 2023). "Further, the genes were also enriched for targets of several transcription factors, like NELFE, E2F4 and CREB1 which are known to play key roles in several cancers, including breast cancer." (PMID 36584096, 2022).
gastric cancer (2 papers, 2021). A primary or metastatic malignant neoplasm involving the stomach. "In conclusion, NELFE acts as an oncogene in gastric cancer and can be used as a potential therapeutic target." (PMID 34295816, 2021). "The NELFE protein was generally expressed in gastric cancer cells, and its protein expression level was high in some gastric cancer cell lines, especially in BGC-823 and AGS cells." (PMID 34295816, 2021). "Knockdown of NELFE dramatically inhibits the cell proliferation and metastasis of gastric cancer xenografts in vivo." (PMID 34295816, 2021). "In our study, we systematically examined the promoting effect of an RNA-binding protein (NELFE) in human gastric cancer cells." (PMID 34295816, 2021). "The results showed that knocking down the expression of NELFE can inhibit the proliferation and migration of gastric cancer cells in vitro and in vivo." (PMID 34295816, 2021). "Therefore, NELFE acts as an oncogene in human gastric cancer cells, and targeting NELFE can be considered a potential method for gastric cancer treatment." (PMID 34295816, 2021). "The results showed that cell viability was significantly inhibited after NELFE knockdown in vitro, and the number of colonies formed by AGS and BGC-823 gastric cancer cells decreased significantly." (PMID 34295816, 2021). "NELFE and E2F2 inhibitors could be used as potential therapeutic targets for gastric cancer treatment." (PMID 34295816, 2021). "Overexpression of NELFE was observed in human gastric cancer tissues compared with adjacent nontumor tissues." (PMID 34295816, 2021). "In summary, we have demonstrated that NELFE and E2F2 play a vital role in the proliferation and metastasis of gastric cancer, which may be mediated by effects on the tumor microenvironment." (PMID 34295816, 2021).
metastatic disease (2 papers, 2017 to 2021). "We found NELFE was dramatically overexpressed in GC tumor tissues than in adjacent normal tissues by IHC and qPCR analysis, and metastatic tumors exhibited an increased NELFE expression than primary tumors, indicating the participation of NELFE in GC progression." (PMID 33526068, 2021).
autoimmune disease (1 paper, 2024). A disorder resulting from loss of function or tissue destruction of an organ or multiple organs, arising from humoral or cellular immune responses of the individual to their own tissue constituents. "Six genes in the MHC Class III region, DDX39B, DXO, LSM2, NELFE, PRRC2A, and SKIV2L, encode RBPs and have a well-defined role in post-transcriptional gene regulation and RNA monitoring, and these genes may have important functions in immunity and be associated with autoimmune diseases." (PMID 38770048, 2024).
pancreatic cancer (1 paper, 2020). "Negative elongation factor E (NELFE) promotes metastasis of pancreatic cancer through activating the Wnt/β-catenin signaling pathway and decreasing the NDRG2 mRNA stabilization." (PMID 33251144, 2020).
rheumatic diseases (1 paper, 2025). "It has been discovered that some of these genes (C2, BX511262.2, PRRC2A, BAG6, PBX2, GPSM3, NELFE and AIF1) are significant genetic targets shared by MetS and multiple rheumatic diseases." (PMID 39789419, 2025).
cancer (8 papers, 2017 to 2024). A tumor composed of atypical neoplastic, often pleomorphic cells that invade other tissues. "While these findings implicate a critical role of NELFE in cancers, its specific functions and underlying molecular mechanisms are not fully understood." (PMID 33526068, 2021). "To explore potential mechanisms possible for the cancer-promoting functions of NELFE, we performed gene co-expression analysis using data from Coexpedia database, and 12 co-expressed genes of NELFE were identified in GC." (PMID 33526068, 2021). "Knockdown of NELFE subunit of the NELF complex was shown to result in global RNA pol II elongation in unstressed primary cells and in cancer cells." (PMID 29523821, 2018).
tumor (6 papers, 2019 to 2025). "The higher NELFE expression was observed to be associated with tumor size (p < 0.01), differentiation of tumor (p < 0.01), TNM stage (p < 0.001) and lymph node metastasis (p < 0.001) of GC." (PMID 34295816, 2021). "Among the 10 signaling pathways directly related with tumor progression, Wnt/β-catenin pathway was strongly activated by NELFE overexpression." (PMID 33526068, 2021). "Consistent with the in vitro observations, forced expression of NELFE substantially increased tumor size and tumor weight, while knockdown of NELFE led to opposite results." (PMID 33526068, 2021). "Considering the IHC results that NELFE expression was significantly upregulated in metastatic tumor tissues in comparison with primary tumor tissues, we assumed that NELFE plays a role in tumor metastasis of GC." (PMID 33526068, 2021). "Together, these data indicate that the LCS1m is sufficient for the tumor promoting function of NELFE in HCC, which could be attributed by both NELFE and NELF." (PMID 40313774, 2025). "Consistently, NELFE expression in GC tumor samples was higher than that in normal tissues." (PMID 33526068, 2021). "In vivo, knockdown of NELFE inhibited the tumor formation ability in nude mice." (PMID 34295816, 2021). "Furthermore, we identified a subset of oncogenic MYC targets regulated by NELFE, called NELFE-dependent MYC targets (NDMTs), in HCC tumor tissue and have functionally validated these findings through in vitro studies." (PMID 30833661, 2019).
infection (2 papers, 2024 to 2025). The state of being infected such as from the introduction of a foreign agent such as serum, vaccine, antigenic substance or organism. "Additionally, the virus appears to modulate transcription factors STAT3/STAT5, NELFE, ATF2, TAF7, and others, enhancing cellular response to infection." (PMID 40725231, 2025).
NELFE also shares sentences with these, for which no sentence is quoted: sarcoidosis (2 papers); colon cancer (1); lung carcinoma (1); osteoporosis (1); triple-negative breast carcinoma (1); viral infections (1).